LAMA5 (laminin subunit alpha 5)
Diseases named in the same sentence as LAMA5 in open-access papers (continued):
Sharing a sentence is not in itself a finding about the gene and the disease.
tumor (continued). "Both the primary tumour and the mesenteric metastases showed significant upregulation of LAMA5 within the different groups of patients with fibrosis, whilst the patients with no fibrosis showed a significant downregulation in the primary tumour compared to the normal SI." (PMID 40998421, 2025). "Proteomic analysis, such as that of pancreatic EV samples, has identified that cancer EVs contain a distinctive protein profile, where tumor-promoting candidates such as LAMA5 (laminin subunit alpha 5), SDCBP (Syndecan Binding Protein) and TENA (Tenascin-A) were found to be overexpressed." (PMID 41226690, 2025). "Seven potential tumor antigens, [SREBF1, LUC7L3, LAMA5, PCGF3, HNRNPH1, KLC4, and OFD1], which were associated with nonsense-mediated mRNA decay factor expression, overall survival, and infiltration of APCs and would thus induce a potent anti-tumor T-cell response." (PMID 39399167, 2024). "In this sense, Matrigel showed a higher amount of Fibulin-1 and LAMA5 laminin subunit, two components previously related to the inhibition of tumor progression processes because they mediate different cell attachment, migration, and organization processes into tissues." (PMID 36059712, 2022). "Although these data suggest an association between LAMA5, CD8+ T cell density and tumor prognosis, they must be taken with caution since LAMA5 mRNA levels recorded in these databases are derived from the whole tumor tissue, without distinction between neoplastic and endothelial cells." (PMID 35267534, 2022). "In conclusion, this study shows that SOD3 represses the transcription of LAMA5 in tumor ECs." (PMID 35267534, 2022). "Tumor-promoting candidates LAMA5, SDCBP and TENA were consistently upregulated in PDAC EVs." (PMID 35241737, 2022). "Moreover, our findings also implicate the release of MMP1-derived LAMA5 fragments with bioactive activity, into the tumour microenvironment." (PMID 27324842, 2016). "Importantly, the morphological changes we identified in vessels from LAMA5-deficient tumours are in keeping with those seen in mice lacking LAMA5, which demonstrate a deficiency in branching angiogenesis during early embryogenesis." (PMID 31064120, 2019). "Therefore in the future, simultaneous inhibition of integrin αvβ3 with MMP1 and LAMA5 may provide greater efficacy, and an alternate approach to destabilize tumour vasculature." (PMID 27324842, 2016). "In our study, we identified a series of potential tumor antigens, including SREBF1, LUC7L3, LAMA5, PCGF3, HNRNPH1, KLC4, and OFD1, by systematically analyzing alternative splicing and mutation of genes in patients with HNSCC." (PMID 36467412, 2022). "Conversely, proteins of interest in tumor-bearing rats elevated following OKN-007 treatment included ABCA6, ADAMTS18, VWA8, MACF1, and LAMA5." (PMID 35053843, 2022). "Conversely, proteins of interest in tumor-bearing rats that were elevated following OKN-007 treatment included ABCA6, ADAMTS18, VWA8, MACF1, and LAMA5." (PMID 35053843, 2022). "The tumor suppressor miR-200 affects EMT and tumor cell metastasis by modulating the cell adhesion molecule E-cadherin and the ECM proteins COL6A1, LAMA5, LAMB2, LAMC2, and Fibronectin." (PMID 34769264, 2021). "High levels of SOD3 in the milieu of EG7-SOD3 tumors grafted in syngeneic mice or EG7 tumors implanted in SOD3EC-Tg mice were also correlated with a reduction in laminin α5 staining intensity in tumor blood vessels, supporting a role for SOD3/LAMA5 interactions in vivo." (PMID 35267534, 2022). "CNGs associated with poor outcome harboured transcription factors GATA3, GATA5, MLLT10, and TAF3 frequently amplified in HBCs15,19,28,41–43, EMT markers VIM, LAMA5, and ZEB121, and several genes enriching biological processes enhancing tumour-cell migration and motility." (PMID 31969654, 2020).
tumor (continued). "LAMA5 expression was increased in cells grown in media conditioned by metastasis-derived myeloid cells, while no such effect was apparent for tumour cells grown in media derived from naïve myeloid cells." (PMID 31064120, 2019). "However, genome-scale CRISPR-Cas9 knockout screens showed that LAMA5 depletion resulted in nearly zero in almost all types of cancers, suggesting LAMA5 was not required for tumor cell survival." (PMID 38321088, 2024). "Substantial differences between tumor and neighboring healthy cortex were found in both interstitial matrix proteins, such as collagen 6 (COL6A1, COL6A2, COL6A3), and basement membrane components such as collagen 4 (COL4A1, COL4A2) and laminins (LAMA5, LAMA4, LAMB1, LAMB2, LAMC1)." (PMID 34884982, 2021).
cancer (40 papers, 2010 to 2025). A tumor composed of atypical neoplastic, often pleomorphic cells that invade other tissues. "Basal cell adhesion molecule (BCAM) is a laminin α5 (LAMA5) binding membrane‐bound protein with a putative role in cancer." (PMID 36647260, 2023). "Subsequently, we showed that Lama4 and Lama5 expression dynamically react to diverse immune and tolerance influences, including cancer, gut microbiota, and allotransplantation in mice." (PMID 35775481, 2022). "In many types of cancer, LAMA5 has been observed to be highly expressed and is a possible candidate for targeting angiogenesis in cancer." (PMID 36467412, 2022). "LAMA5 is an important component of the extracellular matrix, which can regulate cell adhesion and promote cancer cell metastasis." (PMID 31959150, 2020). "Down-regulation of LAMA5 in cancer cells impaired liver metastatic growth and resulted in reduced intra-tumoural vessel branching and increased the expression of Notch pathway genes in metastasis-derived endothelia." (PMID 31064120, 2019). "To identify potential myeloid-derived factors responsible for promoting LAMA5 expression in cancer cells, we profiled the conditioned media from naïve and liver metastasis-derived CD11b+ cells using protein cytokine arrays." (PMID 31064120, 2019). "Additional variants, including MUC5B, DNAH11, ANK2, and LAMA5, which were not part of tier-1 genes but has been reported in other gastrointestinal patients (according to the Cancer Browser) were also consistently detected." (PMID 37878600, 2023). "On the other hand, BCAM loosens the structure of spheroids, where LAMA5–integrin β1 interaction is essential to maximise compaction, thereby promoting the dispersion of cancer cell spheroids at target sites, which in turn is likely to contribute to peritoneal metastatic spread." (PMID 36647260, 2023). "Thus, the Lama5 gene links two markers of cancer progression (Inflammation and Angiogenesis) to extracellular matrix (ECM) protein deposition." (PMID 35783385, 2022). "These CNV regions encode nineteen known genes, and some of which have been shown to affect aging-related phenotypes such as the shortening of telomere length (ZNF208), the risk of cancer (FOXA1, LAMA5, ZNF716), and vascular and immune-related diseases (ARHGEF10, TOR2A, SH2D3C)." (PMID 29883365, 2018). "AREG, ER, JAGL1, and LAMA5 are predominantly reported for proliferation induction in cancer cells." (PMID 20096135, 2010). "Further experiments are required to address whether additional functions of Lama5 partake mammary gland biology in vivo and whether the mechanisms described here contribute to pathologies with distorted tissue organization, such as cancer." (PMID 34128985, 2021). "For example, laminin subunit alpha-5 fragments were able to bind with αvβ3 integrin to promote angiogenesis of endothelial cells, and laminin-5 could interact with its receptor α6β4 integrin to promote cancer cell growth and survival." (PMID 28706483, 2017). "The dysregulation of cell migration, adhesion and invasion regulators, such as MCAM/CD146, ALCAM/CD166, CAR/CXADR, EFNA1, LAMA5, CD73/NT5E and integrins, contributes to cancer progression and metastasis." (PMID 40314078, 2025). "Of all the datasets investigated, LAMA3, LAMA5, LAMB3 and LAMC2 were found to be commonly upregulated in cancer when compared to adjacent tissue samples as well as in CCA tissues and cell lines." (PMID 38114514, 2023). "Subunit gamma-1 (LAMC1) was downregulated in all four cancer types, while all other subunits showed lower expression levels in SCLC; LAMC2, LAMA5, LAMB2 in LCC; and LAMA5, LAMB2, LAMA3 in AC as well." (PMID 35681609, 2022). "Recently, vitamin D compounds have also been shown to inhibit cancer stem cells by down regulating cancer stem cell markers (like OCT4, CD44, and LAMA5) and by inhibiting Notch signaling molecules (involved in cancer stem cell maintenance)." (PMID 29849001, 2018).
cancer (continued). "The 20q13.33 region overlapped with several cancer related genes such as CDH4, LAMA5, RPS21, KIAA1510, TNFRSF6B (M68, DcR3), RTEL, EEF1A2 and PTK6." (PMID 24165089, 2013). "Meanwhile, other cell-cell adhesion-related molecules, such as laminins (LAMA4, LAMA5, LAMB1, LAMB2 and LAMC2) and integrins (ITGA5, ITGA5, ITGB5, ITGA11 and ITGBL1), are elevated in cancer tissues." (PMID 22905095, 2012). "Among the listed ECM genes, two types were noted, those that were low in mono-cultures and high in co-cultures (e.g. COL1A, FN, LAMA1, primarily fibroblast-derived) and those that were high in both mono- and co-cultures (e.g. LAMA5 and LAMB1, primarily cancer cell-derived)." (PMID 39011470, 2024). "Of 94 germline familial variants identified with predicted functional impact, 37 SNPs/indels were detected in 28 genes, 2 of which (MLH1 and PRH1-TAS2R14) have known association with CRC and 4 others (PPP1R13B, LAMA5, FTO, and NLRP14) have known association with non-CRC cancers." (PMID 37627102, 2023). "Therefore, we inferred that the chromosome amplicon 20q13.33 might be the work unit in which PSMA7 but at least not LAMA5 functioned as a cancer-promoting factor." (PMID 38321088, 2024). "Supporting this hypothesis, analysis of TCGA data with TIMER algorithm showed a negative correlation between LAMA5 mRNA levels and the intratumor CD8+ T cell signature for some cancers types, including stomach, lung and ovarian." (PMID 35267534, 2022).
kidney disease (3 papers, 2018 to 2022). "Here, we identified what we believe to be a novel heterozygous LAMA5 variant, V3687M, as the gene variant possibly responsible for a renal disease: slowly progressive FSGS." (PMID 36173685, 2022). "However, genetic kidney diseases caused by heterozygous LAMA5 variants have been difficult to identify, despite the recognition of several LAMA5 variants associated with renal disease." (PMID 36173685, 2022). "However, the importance of heterozygous LAMA5 variants in human NS and kidney disease has remained unclear; a heterozygous LAMA5 variant has not been definitively found to cause monogenic human kidney disease, including NS or FSGS." (PMID 36173685, 2022).
neurological diseases (2 papers, 2022 to 2025). "The highest expression of LAMA5 in the human brain provided an anatomical basis for the association between LAMA5 and neurological diseases." (PMID 35663266, 2022). "However, the LAMA5 gene, which encodes one of the indispensable parts of the heterotrimers, has not been confirmed to be associated with neurological disorders." (PMID 35663266, 2022).
heart diseases (1 paper, 2025). "LAMA5 is one of the non‐collagen components of the extracellular matrix, and until recent years, there has been no related research in the field of heart disease." (PMID 40642838, 2025).
LAMA5 also shares sentences with these, for which no sentence is quoted: infection (3 papers); glioblastoma (2); metastatic cancer (2); alopecia (1); benign colon neoplasm (1); bent bone dysplasia (1); breast tumors (1); cardiomyopathy (1); colitis (1); conduction disorders (1); congenital heart defects (1); diabetes (1); dwarfism (1); ectodermal dysplasia (1); esophagitis (1); fibrosarcoma (1); fibrosis (1); focal seizures (1); glioma (1); hepatocellular carcinoma (1); intracerebral hemorrhage (1); intracranial hemorrhage (1); kyphomelic dysplasia (1); leukemia (1); liver cancer (1); lung disease (1); melanoma (1); metastasis (1); muscular dystrophy (1); Myocardial Hypertrophy (1).
A further 16 diseases each share a sentence with LAMA5 in 1 paper.